CD4 (CD4 molecule)
Diseases named in the same sentence as CD4 in open-access papers (continued):
Sharing a sentence is not in itself a finding about the gene and the disease.
AIDS (continued). "AIDS-related malignancies in HIV-infected patients are mainly related to current immunodeficiency and viral infections, but other factors such as a low nadir CD4 count may also be involved." (PMID 26642314, 2015). "By using data extracted from the Chinese HIV/AIDS Comprehensive Response Information Management System (CRIMS), we aimed to identify trends in the proportion of individuals who received timely baseline CD4 cell count testing within 6 months of HIV diagnosis in China from 2006 to 2012." (PMID 24901790, 2014). "Interestingly, logistic regression showed that neither CD4 cell count (OR 0.73, 95% CI: 0.47–1.09 per 100 cells; p=0.129) nor AIDS prior to HI (OR 0.34, 95% CI: 0.04–2.51; p=0.283) was associated, with DTH normalization." (PMID 24499779, 2014). "In addition, natural CD4 down-modulation by memory CD4+ T cells in vivo protects African green monkeys from developing AIDS after infection with simian immunodeficiency virus (SIV), while maintaining the immunological functions normally attributed to CD4+ T cells." (PMID 25460167, 2014). "On the other hand, in the pre-highly active antiretroviral treatment (HAART) era, some untreated patients could reach very low CD4+ T cell counts without progressing to AIDS and showed surprisingly preserved NK cell numbers and function." (PMID 25071766, 2014). "Overall, 232 people (57.1%) with AIDS or a low CD4 count had not received ART by the end of 2010." (PMID 25095830, 2014). "Third, follow-up care and CD4 tests were confined to local resident HIV/AIDS cases in Nanjing, this may not reflect the situation among those temporarily living in Nanjing." (PMID 25050797, 2014). "Likewise, evidence has been published demonstrating that a subpopulation of CD4 T-lymphocytes involved in the CD1-restricted glycolipid antigen presentation pathway in leprosy and TB patients persists in patients with AIDS." (PMID 24797271, 2014). "Specifically, CD4+ T cells have a role in LTNP (long-term non-progression) to AIDS." (PMID 25028990, 2014). "As China continues to develop and expand its national AIDS programs, including the NFATP, it will be critical to have regular assessment and monitoring of the programs' ability to link newly identified HIV-positive individuals to timely CD4 testing and treatment initiation." (PMID 24901790, 2014). "In those with cutaneous anergy and advanced HIV disease, as evidenced by low CD4 cell counts and AIDS diagnoses, the capacity for both CD4 reconstitution and normalization of DTH responses during HAART appears to be similar to that of those without advanced disease." (PMID 24499779, 2014). "Overall, this review suggests that, whenever possible, therapy should be started when CD4 counts are at or above 500 cells/μL rather than waiting for the CD4 to fall to lower counts or the old recommended guidelines (350 cells/μL) in order to prevent mortality and morbidity due to AIDS progression." (PMID 24778646, 2014). "Since this finding was not attributable to low CD4 counts or the presence of AIDS diagnoses, other immunologic and/or genetic aspects may have contributed to the lack of DTH responses in this group." (PMID 24499779, 2014). "Since non-response to HBV vaccine has been associated with HIV disease progression in those with relatively preserved CD4 counts, we also studied the longitudinal development of AIDS or death outcomes for HIC and non-controllers with documented HBV vaccine responses." (PMID 25144773, 2014). "In ART-CC participants, the lowest SMR was seen in men who have sex with men (MSM), who did not have AIDS at cART initiation and who had attained a viral load of 500 copies/ml or lower and a CD4 cell count of 350 cells/mm3 or higher by 6 months after starting cART." (PMID 24283830, 2013). "Patients with CD4 T cell counts below 100 cells/μl are at high risk to develop CMV-related disease and CMV-seropositive HIV patients progress significantly faster to AIDS than their CMV negative counterparts." (PMID 23717308, 2013).
AIDS (continued). "Persons with CD4 ≤350 cells/μL or diagnosed with AIDS (regardless of the CD4 cell count) were defined as late presenters (LP); persons with CD4 ≤ 200 cells/μL or AIDS (regardless of the CD4 cell count) were defined as presenting with advanced HIV disease (AHD)." (PMID 23537210, 2013). "Firstly, we did not have information on severity of disease at HIV diagnosis (CD4+ T-cells counts) and the virus load at AIDS diagnosis for many cases (data not shown), which might affect our results." (PMID 24376638, 2013). "The number and functionality of CD4+ T cells constantly decrease during HIV disease progression, although progressive impairment and massive deregulation of all players of the immune system are observed in infected individuals, ultimately leading to the development of AIDS." (PMID 23577012, 2013). "The odds of progressing to AIDS and death were not significantly higher among subtype D compared to subtype A possibly because of the lower proportion of participants progressing to these end points than that progressing to CD4 cell counts ≤250 cells/mm3." (PMID 23951241, 2013). "Because of social or economic factors, HIV infectors might be concurrently diagnosed with AIDS at low CD4+ T-cell counts for lack of adequate care to monitor the infection and institute treatment." (PMID 24376638, 2013). "We propose that the expression of selected RNA-based HIV-1 inhibitors in the CD4+ cells derived from GM-HSPC will protect them from HIV-1 infection and results in a sufficient immune repertoire to control HIV-1 viremia resulting in a functional cure for HIV-1/AIDS." (PMID 24284880, 2013). "However, 40%–60% of HIV-positive individuals in developed countries are not diagnosed until they have a low CD4 count or an AIDS-defining illness." (PMID 24137103, 2013). "This “double negative” lymphocyte population is preserved even in the rare SIV-infected SMs with extremely low (<50 cell/ul) CD4+ T cell counts and may explain the lack of AIDS in these animals." (PMID 24009514, 2013). "However, it is not clear what clinical impact continuing to prescribe ART for late-stage AIDS patients who demonstrate neither suppression of HIV replication nor substantive improvement in absolute CD4+T cell count has in the modern ART era." (PMID 24260125, 2013). "The comparison of septic shock patients with and without HIV/AIDS revealed a predominantly young HIV/AIDS population, that were admitted with infections related to low CD4 levels; however, pneumonia was the most common infection in the HIV/AIDS and non-HIV patients." (PMID 23874739, 2013). "For example, patients with HAART failure and deep immunological deficiency, patients with AIDS classifying diseases but who never had antiretroviral therapy, or patients in the early stage of the HIV infection with high CD4 cell count will probably have very different outcomes." (PMID 22762133, 2012). "If integration into CD27 affects the differentiation or activation of host CD4+ T cells, such arrest may contribute to the observed lack of help by CD4+ T cells and the development of AIDS." (PMID 23209625, 2012). "We determined various factors that influenced patient satisfaction with HIV/AIDS care and treatment services, including levels of the health service administration, socioeconomic status (gender, marital status, and income), duration of ART, CD4 cell counts and drug use behavior." (PMID 23071611, 2012). "Importantly, the robustness of our findings regarding the effects of the most common truncation mechanisms and the exclusion of individuals with only one CD4 measurement while ART-naïve and AIDS-free has been investigated through a series of sensitivity analyses." (PMID 22412867, 2012). "However, rates of morbidity and mortality including both AIDS- and non-AIDS-related events increase substantially with persistent low CD4+ cell counts." (PMID 22474480, 2012).
AIDS (continued). "The median CD4 cell count was 169·5 cells per μL (IQR 100–233), about two-thirds of patients had a CD4 cell count of less than 200 cells per μL, and about a third of patients were assessed as having WHO stage 3 or stage 4 (AIDS) disease before tuberculosis screening." (PMID 22015305, 2012). "Furthermore, no study has directly compared time from HIV seroconversion to treatment initiation, clinical AIDS (i.e. not including CD4<200 cells//μL), or death in SSA and high-income countries." (PMID 22412867, 2012). "Of the 3,633 HIV diagnoses, 886 (24.4%) were classified as having AIDS according to the CDC definition (of whom 69.4% had a CD4 count < 200 cells/μL and no AIDS-defining illness) and a further 512 (14%) were classified as long-standing infections based on AI results." (PMID 22433313, 2012). "It has been reported that CD4-negative cells such as liver, kidney, and CD8+ T cells are infected with the CD4-independent HIV-1 in AIDS patients, and such CD4-independent variants are thought to be associated with hepatitis, nephropathy, and CD8+ T cell dysfunction in AIDS patients." (PMID 21541353, 2011). "However, for resource-limited countries, where viral load testing is often not available for the diagnosis of AIDS, the CD4 cell count and symptoms are the main indicators for initiating HAART." (PMID 21241494, 2011). "Since the median CD4 cell count at which HIV-positive people present with TB is about 200/mm3, most of the short term reduction in AIDS-related TB is gained if people start ART when their CD4 cell count is below 350/mm3, but eliminating AIDS-related TB in the long term will rely on eliminating HIV." (PMID 21999772, 2011). "This portable CD4 count platform displays agreement with the FACSCalibur results and has the potential to expand access to HIV and AIDS monitoring using fingerprick volume of whole blood and helping people who suffer from HIV and AIDS in resource-limited settings." (PMID 21754988, 2011). "ART costs in the standard group were US$81 per person over the median follow-up time of 21 mo because, even through these participants did not initiate ART early, 39% of them subsequently had a CD4 cell count measurement ≤200 cells/mm3 or developed an AIDS-defining illness and initiated ART." (PMID 21949643, 2011). "The selection of patients with CD4+ T cell count nadirs >200 cells/μl and without previous history of OI or AIDs defining illnesses may have contributed to the absence of clinical events in the intermittent ART arm." (PMID 21738668, 2011). "First, natural hosts of SIV (HIV-like simian immunodeficiency virus), monkeys from Africa, do not show immune activation, do not lose their CD4+ T cells and do not evolve to AIDS whereas asian monkeys, nonnatural hosts, develop the pathology after SIV infection." (PMID 21994747, 2011). "However the reverse is not necessarily true—sudden falls in CD4 cell count are not always a precursor to AIDS." (PMID 20186270, 2010). "However, data from the 2007 Kenya AIDS Indicator Survey shows that of people eligible for HAART (with a CD4 count of less than 250), 57% have no idea that they have HIV." (PMID 20205768, 2010). "The low T CD4 cell counts among those patients with AVL/HIV-AIDS after remission, even in the absence of detectable viral load may have important implications for the HAART monitoring." (PMID 21171992, 2010). "There were not statistically significant differences between patients who did or did not have AIDS, CD4 nadir <100 cells/mm3, did or did not have not clinical toxicity (peripheral neuropathy or pancreatitis), HALS, HCV infection, and metabolic syndrome with respect to plasma uridine concentrations." (PMID 21085568, 2010). "Because activated CD4+ T cells are the main target for HIV-1 infection in vivo, we propose that, even if not essential for infection, host cell factors contributing to maximise the rate of HIV-1 infection may play a role in AIDS pathogenesis." (PMID 19193229, 2009).
AIDS (continued). "Alternatively, anemia may be a surrogate marker for some aspect of disease progression not captured by controlling for CD4 count and clinical AIDS diagnosis." (PMID 19922646, 2009). "Interestingly, none of the SIVsmm-infected SMs with persistent dramatic CD4+ T cell depletion developed AIDS." (PMID 18636106, 2008). "Therefore, it was plausible that although the ZNRD1-C allele did not have a direct impact on disease progression rates to AIDS it influenced surrogate markers of disease (e.g., viral load, baseline CD4+ T cell count)." (PMID 18982067, 2008). "Among the progressors, significantly higher levels of the anti-CD4bs Abs were produced by rapid progressors (with declining CD4 counts of > 53 cells/mm3/6 months) prior to development of AIDS than by slow progressors (with no CD4 decline in 7 years of follow-up)." (PMID 18638381, 2008). "Fewer OI diagnoses are reported at the time of AIDS diagnosis because immunologically-defined AIDS usually occurs before an AIDS-OI; over 60% of new AIDS cases in the United States are reported based on CD4 count, with no AIDS-OI." (PMID 17850671, 2007). "This difference does not mean that CD4 count has the larger predictive value for AIDS progression." (PMID 17888148, 2007). "A study of HIV positive Australian men without AIDS found that the time to develop AIDS could be predicted by the CD4 count, CD4 percentage and the rate of change for each." (PMID 16916461, 2006). "Also, if our experience with the increase in CD4 cells after treatment with low-dose TGIK could be reproduced, GIK may prove helpful in the treatment of AIDS." (PMID 16111485, 2005). "Importantly, when we reintroduced GJB2 into CD4+ T cells isolated from anti-retroviral therapy (ART)-treated patients, we observed that GJB2 overexpression still inhibited HIV-1 spread in these cells ex vivo, suggesting a potential application for combating HIV/AIDS." (PMID 40980890, 2025). "Our results need confirmation, and additional studies should determine whether the increased risk of AIDS and non‐AIDS related events objectified in cohorts of INR with low CD4/CD8 is due, in INR, to low CD4 counts or NK counts, rather than CD8 activation, or both." (PMID 39868926, 2025). "The lower CD4+ T cell count and higher viral titer correlate with a series of bacterial, viral, fungal, and protozoal infections, which together with neurological symptoms characterize the AIDS stage of the viral infection, which without treatment leads to death in 3 years or less." (PMID 38667150, 2024). "Before the initiative of universal antiretroviral therapy (ART), it was widely noted that some children would remain AIDS-free for more than 10 years and could maintain normal-for-age clusters of differentiation (CD4+) T-cell counts – so-called long-term nonprogressors (LTNP)." (PMID 38036259, 2024). "However, through ex-vivo characterization of CD4 + T cells from HIV controllers, we show that controllers have significantly reduced CCR5 expression which could partly account for the reduced T cell depletion and delayed progression to AIDS." (PMID 37231494, 2023). "Factors influencing survival time in people living with HIV/AIDS were sex, age at diagnosis, household registration, the timing of treatment, occupation, marriage status, ethnicity, education level, route of transmission, whether receiving ART, and the count of CD4+T cells at baseline." (PMID 37679721, 2023). "Moreover, for clinicians, the CD4+ cell count recovery of CRF01_AE and cluster 1 individual should be monitored more closely because these patients may develop AIDS more quickly than patients who are not infected with this genotype." (PMID 34895083, 2022). "Thus, CD4+ cell count recovery after initiation of ART is a potential indicator of HIV patient’s clinical outcome and an increase in CD4+ cell count indicates a favorable outcome related with both AIDS and non–AIDS-related conditions and the improvement in life expectancy." (PMID 35324948, 2022).
AIDS (continued). "Besides, high sTNF-R1 levels are associated with loss of CD4+ T-cells in HIV-ECs with a sustained virological control and HIV-1 individuals on ART, and with development of AIDS and non-AIDS events during suppressive ART." (PMID 35372109, 2022). "Early in AIDS and especially after BM transplantation, the high ratio of normal versus HIV-infected hematopoietic cells may prevent myeloid cell expansion, either directly as in non-Tg/Tg chimera or by preventing their infection, as shown in CD4+ T cell-depleted SIV-infected macaques." (PMID 34106001, 2021). "We hypothesize, that severely immunosuppressed AIDS patients (CD4+ T cell count <250 cells/μL) are not able to mount a proper immune response to cryptococcal infection, and, therefore, no increase in anti-cryptococcal IgG titers is detectable in these patients." (PMID 34367172, 2021). "HIV/AIDS without previous diagnosis, viral load and CD4+ unknown." (PMID 35528625, 2021). "According to these observations, the 2011 Chinese National Guidelines for HIV/AIDS Diagnosis and Treatment recommended that providers weigh the benefits of NVP carefully against the risk of severe hepatoxicity in patients with baseline CD4 counts above 250 cells/mm3 regardless of the patient’s sex." (PMID 31939111, 2020). "Finally, lack of CD4 testing in the immunological diagnosis of AIDS-related illnesses and deaths may constitute a classification bias." (PMID 33425177, 2020). "This study discriminated PIR and AIR among patients with acquired immunodeficiency syndrome (AIDS) and <200 CD4+ T cells/μL at ART onset, not using any of the many clinical criteria reported in the literature, but instead using clustering analysis of longitudinal data." (PMID 30804925, 2019). "Therefore, the present study investigated the situation of late presentation (CD4 < 350/mm3, or AIDS-defining event regardless of CD4 count) and advanced HIV disease (CD4 < 200/mm3, or AIDS-defining event regardless of CD4 count) among patients with newly diagnosed HIV/AIDS." (PMID 30876476, 2019). "A lower CD4/CD8 ratio can be interpreted as a measure of dysregulation of a patient’s immune system, known as immunological risk phenotype, in the general population and has been clearly associated with a higher risk of AIDS and non-AIDS events in HIV-infected patients." (PMID 29807541, 2018). "We investigated whether the CD4:CD8 ratio or CD8 counts were independently associated with all-cause, AIDS, and non-AIDS mortality in patients treated with ART with suppressed VL and CD4 count >350 cells/μL using data from the Antiretroviral Therapy Cohort Collaboration (ART-CC)." (PMID 28903507, 2017). "In acute HIV infection, CD4+ T cells rapidly decline in the gut and in the periphery, followed by partial CD4+ T cell recovery, and then an inexorable depletion of this cell population over time in untreated individuals, leading to AIDS within 6–10 years, though this is not universal." (PMID 29085369, 2017). "Thus, early HIV diagnosis and treatment irrespective of CD4 count, early screening, and use of IPT in HIV-infected patients in Ghana may reduce overall AIDS-associated mortality." (PMID 28819470, 2017). "First, we defined CD4 < 350 cells/μL as a time-to-event endpoint in HIV/AIDS progression, and we could not exclude the possibility that the standards of baseline CD4 count and progression CD4 count were so approach that the judgment of HIV/AIDS progression might be not specific enough." (PMID 28484257, 2017). "Thus the European Late Presenter Group (ELPG) proposed a consensus definition of late presentation based on CD4 count or clinical symptoms: “Persons presenting for care with a CD4 count below 350 cells/μL or presenting with an AIDS-defining event, regardless of the CD4 cell count” in 2011." (PMID 26412578, 2015). "Furthermore, the successful disruption of CXCR4 in Rhesus macaque CD4+ T cells may accelerate gene therapy studies for AIDS in non-human primate models." (PMID 26481100, 2015).